BRCA1 (BRCA1 DNA repair associated)
Diseases named in the same sentence as BRCA1 in open-access papers (continued):
Sharing a sentence is not in itself a finding about the gene and the disease.
tumor (continued). "After adjustment for family history, tumor histology and tumor grade, patients affected by TNBC showed a 323 % higher risk of BRCA1 mutations than non-TNBC patients (RP = 4.23; 95 % CI 2.50–7.14; P < 0.0001)." (PMID 27553291, 2016). "Due to the frequent LOH in SH individuals, we examined the hypothesis that either BRCA1 or BRCA2 would be lost in each of the TH individuals due to LOH, and that whichever gene was lost could have an impact on their tumor characteristics." (PMID 27836010, 2016). "BRCA1 gene located on chromosome 17q21 and BRCA2 gene located on chromosome 13q12 are tumor suppressor genes involved in maintaining of genome integrity by engaging in many processes such as repair of DNA double strand breaks, cell cycle control and transcription." (PMID 27129401, 2016). "While this only contained one of our original cell line defined BRCA1/ NFκB target genes (CXCL10) this is not overly surprising as this is a tumour derived classifier." (PMID 26943587, 2016). "The levels of tumour DNA methylation were generally higher in the samples with lower levels of BRCA1 protein although the differences were not statistically significant." (PMID 27463681, 2016). "As observed, none of the tumor clusters are characterized by a particular BRCA1 expression status, but they do carry common alterations." (PMID 26979459, 2016). "Studies that investigate in depth the functional relationship between BRCA1 and the vitamin D/VDR axis could lead to important discoveries about the role of these tumor suppressor pathways in a variety of aging-related diseases." (PMID 27145372, 2016). "The role of BRCA1 in Pol-III transcription could be different and better aligned with classical functions of tumour suppressor targeting expression of oncogenes." (PMID 27589844, 2016). "However, although we evaluated the nuclear expression of PARP1, BRCA1, and BRCA2 based on the previous reports, the expression of PARP1, BRCA1, and BRCA2 are seen in both the cytoplasm and nuclei of tumor cells." (PMID 27643881, 2016). "We would suggest however, that these patients probably would not benefit from the addition of docetaxel to their regime regardless of lymph-node involvement, given that tumours with dysfunctional BRCA1 are less likely to respond to anti-microtubule agents." (PMID 26943587, 2016). "Preclinical studies have demonstrated that tumor cell lines lacking functional BRCA1 or BRCA2 are sensitive to PARP inhibitors." (PMID 27285752, 2016). "This can include the only clinically prosecuted synthetic lethal pairing where genetic loss of BRCA1/2 leads to sensitivity to PARP1/2 inhibition with Lynparza (Olaparib, AZD2281), since PARP1/2 are not reported to show genetic loss in tumours." (PMID 26781748, 2016). "In agreement with the high protein expression level in the GBM, patient 2 did not present any BRCA1 promoter methylation in this tumour." (PMID 25880076, 2015). "The heterogeneity of the reported results did not allow a conclusion regarding the contribution of BRCA1/2 status and tumour features to a worse survival." (PMID 25816289, 2015). "Previously, impaired BRCA1/2 genes have been known to play an important role in conferring sensitivity to PARP1 inhibitors, providing a well-accepted DNA repair mechanism for the tumor-suppressive effect of PARP1 inhibitors." (PMID 26540566, 2015).
tumor (continued). "Of the 149 tumor tissues, 95 cases (63.8%) and 54 cases (36.2%) expressed PIG3 at high and low levels, respectively, while 97 cases (65.1%) and 52 cases (34.9%) expressed BRCA1 at high and low levels, respectively." (PMID 25797244, 2015). "It is possible that in these cell lines BRCA1 expression was affected by epigenetic silencing of the promoter, as has been described by the TCGA to have occurred in approximately 12% of 316 HGS EOC tumor samples." (PMID 26622941, 2015). "Firstly, the BRCA1 hypermethylation exhibited a higher percentage of the smaller size primary tumor (T1 and T2, tumor size ≤5 cm) compared to the BRCA1 non-methylation ( 58.1% vs. 49.1%)." (PMID 25789047, 2015). "Given that the mechanisms of BRCA1 tumor suppression have not yet been fully elucidated, we summarize and explore the potential role of BRCA1 in response to ROS and carcinogenesis in the context of its known functions." (PMID 24704793, 2014). "Expression of HOXA9 in SCC4 cells also resulted in increased expression of BRCA1, suggesting that, in addition to promoting growth, reduced expression of HOXA9 may contribute to tumor genome instability." (PMID 24886209, 2014). "Interestingly, when adding the E2F3 expression to the FANCA and BRCA1 gene expression correlation, tumor samples with relatively low expression of FANCA and BRCA1 had also low E2F3 and vice versa." (PMID 25161863, 2014). "We present the results of integrated analysis of miR/mRNA data from the same tumor tissue samples to identify genes that could differentiate between tumor harvested from young patients (aged ≤35 years) with familial BC and those from sporadic BC, not harboring BRCA1/BRCA2 mutations." (PMID 25006670, 2014). "Mice expressing the enzymatically dead mutant BRCA1(I26A) are no more tumor prone than those expressing wild-type protein." (PMID 25131202, 2014). "In contrast, the Brca1-wild type tumor model did not respond to olaparib despite PARP inhibition in tumors, indicating the importance of damaged HR repair to olaparib efficacy." (PMID 24748377, 2014). "Tumor RRM1, ERCC1, and BRCA1 mRNA expression levels were analyzed by quantitative RT-PCR." (PMID 24591771, 2014). "In contrast, increased DNA damage after cisplatin treatment in Brca1-wild type tumors did not result in decreased tumor volume likely due to effective DNA repair." (PMID 24748377, 2014). "BRCA1 tumours, being predominantly basal-like, do not express ER and therefore show lower expression of ER targets compared to BRCA2 tumours, which are predominantly luminal-like and express ER." (PMID 25521701, 2014). "On the other hand, YY1 could suppress tumorigenesis by upregulating tumor suppressor genes such as HLJ1 and BRCA1, and inhibiting c-myc function by direct interaction." (PMID 24884523, 2014). "Biochemical analysis indicated that pathogenic forms of the BRCT domain of BRCA1 protein (e.g. M1775R) do not bind to BRAT1, suggesting BRCA1/BRAT1 interaction is important for BRCA1’s tumor-suppressive functions." (PMID 25070371, 2014). "Certainly, it might be speculated that BRCA1 and BRCA2 are important for tumor suppression by virtue of their function in HRR." (PMID 23675572, 2013). "In this critical context, it could be of great interest to examine the expression of BRCA1 that may function as a potential regulator of TOP1 expression and therefore be determinant for the efficiency of the anti-tumour treatment." (PMID 23805307, 2013).
tumor (continued). "One tumour arising in a BRCA1 carrier had an exon 20 PIK3CA mutation, five PIK3CA mutations occurred in BRCAX males whereas no PIK3CA mutation were identified in tumours from BRCA2 mutation carriers." (PMID 23971979, 2013). "As a result, extremely short telomeres in BRCA1 over-expressing tumor cells did not trigger senescence, apoptosis, or cell cycle arrest." (PMID 23802008, 2013). "Our results indicated that miR-20b could target many tumor suppressors, including PTEN and BRCA1, which were of a particular interest to us, since the inhibitory role of these two genes in proliferation, migration, and cell cycle has been well documented." (PMID 23945289, 2013). "In a patient with a BRCA1 mutation (185delAG), we found FFPE tumor tissue stained with the MS110 antibody was mostly negative and the BRCA1 staining in the FFPE normal tissue was weakly positive." (PMID 23855721, 2013). "However, a strong correlation was observed between the mRNA expression levels of APTX and BRCA1 (rho = 0.53, P < 0.001), APTX and ERCC1 (rho = 0.73, P < 0.001), BRCA1 and ERCC1 (rho = 0.48, P < 0.001) in tumor." (PMID 23517622, 2013). "Both high 53BP1 levels and BRCA1 promoter hypermethylation were observed in three TN tumours and two non-TN tumours." (PMID 24191908, 2013). "Drug sensitivity of these tumor cells was indistinguishable from sensitivity of other RB− (but Brca1 proficient) or RB+ TNBC cell lines (data not shown)." (PMID 24265703, 2013). "miR-20b may serve as an oncomiR that plays a crucial role in breast tumorigenesis by targeting tumor suppressors PTEN and BRCA1." (PMID 23945289, 2013). "Nuclear BRCA1 protein expression was not detectable in the cell line, therefore corroborating the tumor suppressor function of BRCA1 and the pathogenicity of the mutation." (PMID 24137399, 2013). "These occurrences lead to the absence of functional BRCA1 protein and, thus, to genetic instability and tumor development." (PMID 23374397, 2013). "The quantitative DNA methylation analysis of the candidate genes showed higher methylation proportion in the primary tumor tissue than that of the matched normal tissue and the differences were significant for the APC, BIN1, BMP6, BRCA1, CST6, ESR-b, P16, PTEN and TIMP3 promoter regions (P<0.05)." (PMID 22695536, 2012). "Functionally, BAP1 is a nuclear deubiquitinating enzyme that has tumor suppressive activities in conjunction with and also independent of BRCA1." (PMID 22545102, 2012). "Inactivation of Brca1 alone in murine ovarian surface epithelium resulted in an increased accumulation of premalignant changes, but no tumor formation." (PMID 22347400, 2012). "Therefore, tumours with high MAD2 IHC intensity and very long PFS are likely to be highly enriched for BRCA1 inactivation." (PMID 22069160, 2012). "Following immunohistochemical staining of the test cohort, BRCA1-IRIS-positive vs. negative cells was counted in at least 10 high power fields of each tumor." (PMID 22511931, 2012). "Similar to other mediators of checkpoint responses (e.g., BRCA1, MDC1), 53BP1 also contains a highly conserved tandem BRCA1 C-terminal (BRCT) domain, which is essential for tumor-suppressor function via interaction with ezrin-radixin-moesin (ERM) at the plasma membrane." (PMID 22266878, 2012). "A substantial body of work indicates that tumours arising in patients with germline BRCA1 mutations are morphologically and genetically distinct from those arising in carriers of BRCA2 mutations and from tumours in patients lacking mutations." (PMID 22053997, 2011).
tumor (continued). "When we compared misclassifications between the BRCA1 aCGH and MLPA classifiers we found that five BRCA1-mutated tumours were not classified as BRCA1-like with MLPA and five were missed by aCGH (not completely overlapping)." (PMID 22032731, 2011). "The authors in this study reported generally low levels of methylation detected in PB (for most of the samples less than 5%) and furthermore, three patients with BRCA1 methylation in PB DNA did not display BRCA1 methylation in the paired tumor sample." (PMID 22129206, 2011). "More recently, it has been recognised that BRCA1 or BRCA2 mutant tumours are sensitive to PARP inhibitors and thus rapid and inexpensive BRCA1 and BRCA2 testing may be of direct clinical utility." (PMID 21702907, 2011). "Selected CRC target genes involved in apoptosis (BAX), tumor growth (TGFβRII), WNT pathway (AXIN2, TCF4, WISP3), DNA repair (ATM, ATR, BLM, BRCA1, BRCA2, DNAPKcs, MBD4, MRE11, MSH3, MSH6, RAD50, XRCC2) and PI3-kinase signaling (PTEN) were analyzed for mutations in MSI-positive HGG samples." (PMID 21637783, 2011). "Further to previous studies, we have found a significant inverse relationship between the two phenotypes under investigation, BRCA1 and CD44+, indicating that these tumour cells may be a subpopulation of tumourigenic cells." (PMID 23508738, 2011). "At the same time despite of marked methylation in tumor DNA, no methylation of BRCA1 and APC was seen in PB DNA of 4.3% and 2.7% of the patients respectively." (PMID 22129206, 2011). "Only one patient attained a pathological complete response (in tumor but not in axilla); it is thus impossible to correlate response with BRCA1 mRNA levels." (PMID 20209131, 2010). "Although the precise role(s) of BRCA1/BARD1 in tumor suppression have not been fully established, ample evidence indicates that this heterodimer is required to maintain genomic stability following DNA damage (see reviews)." (PMID 21103343, 2010). "It is important to note that in contrast to the BC, the BRCA1 5382insC distribution in women with OC is independent of age, family history, and the number of primary tumours." (PMID 22649661, 2010). "This has been shown to occur with other tumor suppressors including BRCA1, whose NLS-lacking alternatively splice isoforms are transported into the nucleus following DNA damage." (PMID 20844588, 2010). "There was a significant difference in tumor volume after EC between BRCA1-positive and BRCA1-negative baseline foci groups (82.1 ± 17.8% vs 55.7 ± 25.1%, P = 0.0039)." (PMID 20205718, 2010). "BRCA1 protein plays multiple essential functions such as tumor suppressor, transcriptional regulation and DNA repair in normal epithelial cells and stem cells." (PMID 20576130, 2010). "They suggested that the DNA repair and apoptosis pathways were altered in the BRCA1 tumours and that, although most of these were ER negative, ER status alone was not sufficient to discriminate both classes." (PMID 19826428, 2009). "In this series, all BRCA1 tumours showed a double or a single negative hormonal receptorial status, whereas HER2 was invariably negative or only weakly expressed." (PMID 19818148, 2009). "Two of these GII-high subgroups were enriched with either BRCA1- or BRCA2-related tumours whereas the third was not BRCA-related." (PMID 19589159, 2009). "Tumor formation was also not observed in mice in which both Rb and Brca1 were concomitantly inactivated via intrabursal injection of AdCre." (PMID 20046869, 2009).
tumor (continued). "Until recently, the role of the BRCA1/BARD1 heterodimer in tumour suppression had not been evaluated." (PMID 19904273, 2009). "Interestingly, the ESR1-negative tumours were substratified into two groups presenting slight differences in the magnitude of the expression of immune response transcripts and REL/NFκB transcription factors, which could be dependent on the type of BRCA1 germline mutation." (PMID 19826428, 2009). "Three out of five platinum-resistant tumours showed secondary genetic changes in BRCA1, whereas no BRCA1 alterations were observed in three platinum-sensitive tumours." (PMID 19904273, 2009). "Combining the two different platforms involves reduction in array resolution for which reasons the five familial BRCA1 tumours were not included in subsequent analysis." (PMID 19589159, 2009). "The BRCA1-related subgroup was enriched for tumours displaying non-luminal phenotypes (9 of 11, 82%; Fisher's exact test, P = 0.0049) and grade 3+ (8 of 11, 73%)." (PMID 19589159, 2009). "It is now well known that tumor cells lacking BRCA1/2 are highly sensitive to DNA damaging agents like platinum derivatives, as a consequence of impaired genomic damage repair which is induced by different mean." (PMID 19825178, 2009). "In line with this we observed that tumours within the BRCA1-related subgroup primarily display non-luminal phenotypes of which basal-like phenotypes were the most prominent." (PMID 19589159, 2009). "Tumours within the BRCA1- and BRCA2-related genomic subgroups were found to acquire genomic alterations affecting distinct regions of their genomes while also displaying distinct tumour phenotypes." (PMID 19589159, 2009). "Based on the results of experimental models, an exploratory analysis of the relation between BRCA1, RAP 80 and Abraxas mRNA expression was performed in 86 of 111 patients without EGFR mutations for whom sufficient tumor tissue was available." (PMID 19415121, 2009). "It is important to determine the repressive effects of E2F-1 on hTERT transcription in tumor cells with and without the normal BRCA1 protein to determine any variance between BRCA1 status and inhibition of telomerase." (PMID 18366791, 2008). "These tumours showed no BRCA1 methylation using MethyLight or MS-HRM, indicating that methylation of BRCA1 in the peripheral blood corresponds to tumour methylation." (PMID 18269736, 2008). "Interestingly, PTEN may be one of the key genes BRCA1 has to repair to prevent malignant transformation: frequent gross PTEN mutations, involving intragenic chromosome breaks, inversions, deletions and microcopy number aberrations are found in BRCA1-deficient tumours." (PMID 18392054, 2008). "Consistent with other studies, the majority of BRCA1 tumours are high grade and negative for the oestrogen, progesterone and HER2 receptors." (PMID 18627636, 2008). "genistein reduced the size of the tumours by 50%, indicate that genistein can be protective in the absence of functional Brca1." (PMID 18392054, 2008). "Due to early age of tumor onset, patient 1 was also tested for BRCA1/2 (data not shown) and a polymophic change was detected at BRCA2 exon 10 (N372H)." (PMID 19046423, 2008). "Amino-terminal truncations of BRCA1 blocked the ability of the tumor suppressor to inhibit ER activity in these studies." (PMID 16417649, 2006). "Absent/markedly reduced BRCA1 expression was observed in 9/13 BRCA1 methylated tumours, most of which had BRCA1 deletion." (PMID 16846527, 2006). "Nine of the methylated tumours were estimated to have class 1 BRCA1 protein expression, indicating absent or markedly reduced BRCA1 expression." (PMID 16846527, 2006). "BRCA1 interaction with CBP and p300 was shown to occur in a phosphorylation-independent manner through the CREB-binding domain of the coactivators and both the amino and carboxyl termini of the tumor suppressor." (PMID 16417649, 2006).